HDAC4 (histone deacetylase 4)
Description:
Responsible for the deacetylation of lysine residues on the N-terminal part of the core histones (H2A, H2B, H3 and H4). Histone deacetylation gives a tag for epigenetic repression and plays an important role in transcriptional regulation, cell cycle progression and developmental events. Histone deacetylases act via the formation of large multiprotein complexes. Involved in muscle maturation via its interaction with the myocyte enhancer factors such as MEF2A, MEF2C and MEF2D. Involved in the MTA1-mediated epigenetic regulation of ESR1 expression in breast cancer. Deacetylates HSPA1A and HSPA1B at 'Lys-77' leading to their preferential binding to co-chaperone STUB1.
Synonyms: HD4; KIAA0288; HDAC-A; HDACA; HA6116; HDAC-4; AHO3; BDMR; NEDCHF; NEDCHID
Tractability: Small molecule: an approved drug acts on it; a structure with a bound ligand is known; a high-quality ligand is known; it has a binding pocket of medium quality; it belongs to a druggable protein family. PROTAC: UniProt records ubiquitination sites on it; ubiquitination databases record sites on it; its protein half-life has been measured; a small molecule that binds it is known. Other modalities: an approved drug acts on it.
Target class: HDAC class IIa; Histone deacetylase; Epigenetic regulator; Eraser
Gene: Protein-coding gene on chromosome 2 (239,048,168 to 239,401,661, reverse strand). Ensembl gene ENSG00000068024.
Subcellular location: Nucleus; Cytoplasm
Subcellular location (Human Protein Atlas): Nuclear speckles; Cytosol; Nucleoplasm
Pathways (Reactome):
Gene expression (Transcription): Notch-HLH transcription pathway; RUNX2 regulates chondrocyte maturation; RUNX3 regulates p14-ARF
Disease: Constitutive Signaling by NOTCH1 HD+PEST Domain Mutants; Constitutive Signaling by NOTCH1 PEST Domain Mutants
Metabolism of proteins: SUMOylation of chromatin organization proteins; SUMOylation of intracellular receptors
Developmental Biology: Differentiation of naive CD4+ T cells to T helper 2 cells (Th2 cells)
Signal Transduction: NOTCH1 Intracellular Domain Regulates Transcription
Gene Ontology:
Molecular function: DNA-binding transcription activator activity; DNA-binding transcription factor binding; histone binding; histone deacetylase activity; histone deacetylase activity, hydrolytic mechanism; histone deacetylase binding; identical protein binding; molecular adaptor activity; potassium ion binding; protein binding; protein lysine deacetylase activity; RNA polymerase II cis-regulatory region sequence-specific DNA binding; RNA polymerase II-specific DNA-binding transcription factor binding; SUMO transferase activity; transcription cis-regulatory region binding; zinc ion binding
Biological process: chromatin remodeling; negative regulation of gene expression, epigenetic; negative regulation of myotube differentiation; negative regulation of protein refolding; negative regulation of transcription by RNA polymerase II; positive regulation of cell population proliferation; positive regulation of protein sumoylation; positive regulation of transcription by RNA polymerase II; response to interleukin-1; type I interferon-mediated signaling pathway; B cell activation; B cell differentiation; cardiac muscle hypertrophy in response to stress; inflammatory response; negative regulation of glycolytic process; nervous system development; positive regulation of DNA-templated transcription; protein sumoylation; response to denervation involved in regulation of muscle adaptation
Cellular component: chromatin; cytoplasm; cytosol; histone deacetylase complex; nuclear speck; nucleoplasm; nucleus; transcription repressor complex
Genetic constraint (gnomAD): Loss-of-function variants: 16 observed, 126.54 expected, observed/expected ratio (o/e) 0.13, 90% interval 0.085 to 0.19. The upper end of that interval is the gene's LOEUF score, 0.19, which puts it in group 1 of 6, group 1 being the genes least tolerant of losing a copy. Missense variants: 1,122 observed, 1,524.3 expected, observed/expected ratio (o/e) 0.74, 90% interval 0.7 to 0.77. Synonymous variants: 683 observed, 657.89 expected, observed/expected ratio (o/e) 1.04, 90% interval 0.97 to 1.11.
Homologues: Orthologues: chimpanzee HDAC4 (99% identical), macaque HDAC4 (99% identical), dog HDAC4 (94% identical), rat Hdac4 (94% identical), mouse Hdac4 (93% identical), pig HDAC4 (93% identical), guinea pig HDAC4 (92% identical), tropical clawed frog hdac4 (79% identical), zebrafish hdac4 (75% identical), Caenorhabditis elegans hda-5 (11% identical), Caenorhabditis elegans F43G6.4 (8% identical), Caenorhabditis elegans F43G6.17 (7% identical). Paralogues in human: HDAC5 (61% identical), HDAC9 (57% identical), HDAC7 (47% identical), HDAC6 (26% identical), HDAC10 (12% identical), HDAC1 (12% identical), HDAC2 (11% identical), HDAC3 (10% identical), HDAC11 (10% identical), HDAC8 (9% identical).
Diseases named in the same sentence as HDAC4 in open-access papers:
HDAC4 is named in the same sentence as 252 diseases in open-access papers, as found by Europe PMC text mining. Sharing a sentence is not in itself a finding about the gene and the disease. The quoted sentences say what the papers report.
cardiac hypertrophy (53 papers, 2010 to 2025). "Studies have found that Endog deficiency can promote cardiac hypertrophy through reactive oxygen species (ROS) accumulation, activation of the Akt and GSK3β signalling pathways, and HDAC4 and HDAC5 nuclear export." (PMID 40497340, 2025). "In cardiac myocytes, accumulation of activated CaMK2δ in nuclear and perinuclear regions causes HDAC4 nuclear export and transcription of genes related to cardiac hypertrophy." (PMID 35412911, 2022). "Excessive CaMKII activity causes myocardial hypertrophy by catalyzing phosphorylation of HDAC4, leading to cytoplasmic partitioning of HDAC4, and derepression of hypertrophic transcriptional programs." (PMID 32887881, 2020). "Nuclear localization of Nox4 has been reported from other cell types such as human vascular endothelial cells and from cardiomyocytes, in which Nox4 causes histone deacetylase 4 (HDAC4) cysteine oxidation, leading to HDAC4 exit from the nucleus and cardiac hypertrophy." (PMID 25645462, 2015). "Additionally, HDAC4 deficiency can attenuate Ang II-induced cardiac hypertrophy in cardiomyocytes, as well as reducing cardio fibrosis in juvenile rats with overload-induced ventricular hypertrophy." (PMID 34526481, 2021). "Class II HDAC plays an anti‐hypertrophic role in cardiac hypertrophy, with research mainly focused on HDAC4 and HDAC5." (PMID 40497340, 2025). "WWP1 also promotes atypical K27-linked ubiquitin multichain assembly on DVL2 and exacerbates cardiac hypertrophy via the DVL2/CaMKII/HDAC4/MEF2C pathway." (PMID 38674024, 2024). "Ablation of CaMKII in mice significantly relieves stress overload-induced myocardial hypertrophy by preventing sarcoplasmic reticulum Ca2+ leakage or by dephosphorylating histone deacetylase 4 (HDAC4)." (PMID 39795913, 2024). "One of the HDACs which prevents cardiac hypertrophy is HDAC4, which suppresses Mef2 and regulates cardiac hypertrophy." (PMID 36836926, 2023). "In myocyte-specific activated HDAC4 transgenic mice, activated HDAC4 promotes cardiac hypertrophy and fibrosis and exacerbates cardiac dysfunction in infarcted myocardium." (PMID 35954191, 2022). "Another study showed that HDAC4 has the same ability of translocation during cardiac hypertrophy due to the accumulation of reactive oxygen species (ROS)." (PMID 35958418, 2022). "In contrast to the epithelial nuclear HDAC1/2 oxidation, NOX4-dependent oxidation promoted nuclear exit of HDAC4 in mouse heart, while mice with NOX4 deficiency in cardiac myocytes were protected against pressure-overload-induced cardiac hypertrophy." (PMID 33802941, 2021). "It has been reported that the selective 5-HT2A receptor antagonist M100907 suppresses pressure overload-induced cardiac hypertrophy by inhibiting the CaMKII/HDAC4 pathway." (PMID 34959669, 2021). "CKIP-1 is necessary for physiological cardiac hypertrophy in vivo, and for modulating the phosphorylation level of HDAC4 after physiological stress." (PMID 34211403, 2021). "Our previous studies demonstrated that CKIP-1 plays a key role in the suppression of cardiac hypertrophy by promoting HDAC4 dephosphorylation." (PMID 34211403, 2021). "Upregulation of NOX4 by angiotensin II, which is primary in mitochondria of cardiomyocytes, can also result in inducing nuclear export of histone deacetylase 4 (HDAC4), a crucial precursor of cardiac hypertrophy." (PMID 34660744, 2021). "Reviews on HDAC4 reveal functions for this protein in development of cardiac hypertrophy and remodeling." (PMID 34895303, 2021). "CKIP-1 TG mice displayed similar physiological cardiac hypertrophy to WT controls, and the HDAC4 phosphorylation levels in the hearts of CKIP-1 TG mice did not change under physiological stress." (PMID 34211403, 2021). "It was reported that Trx1 inhibited the translocation of HDAC4 and then blocked cardiac hypertrophy signals." (PMID 31968660, 2020). "HDAC4 is a member of the class II HDACs which shuttles between nucleus and cytoplasm to modulate cardiac hypertrophy." (PMID 31968660, 2020).
cardiac hypertrophy (continued). "It was reported that Trx1 can inhibit the translocation of HDAC4 and further repress the cardiac hypertrophy signals, MEF2 and NFAT." (PMID 31968660, 2020). "The overexpression of Ca2+-sensitive, nuclear localized Ca2+/calmodulin-dependent protein kinase II δB (CaMKIIδB) induced cardiac hypertrophy through nuclear Ca2+/CaMKIIδB/HDAC4/MEF2 pathway." (PMID 31065282, 2019). "Class II histone deacetylases HDAC4 and 5 associate with MEF2 and suppress MEF2-specific transcription, thereby regulating cardiac hypertrophy." (PMID 31784580, 2019). "The nuclear export of HDAC4 can inhibit the transcriptional activity of myocyte enhancer factor-1 (MEF2) which is a master positive regulator of cardiac hypertrophy." (PMID 29422872, 2018). "It is of note that NUP155 regulates cardiac hypertrophy through HDAC4, providing additional evidence for the potential role of nups as epigenomic regulators." (PMID 29848314, 2018). "CKIP-1 can suppress pathological cardiac hypertrophy through promoting HDAC4 dephosphorylation by recruiting PP2A." (PMID 28402261, 2017). "Phosphorylated HDAC4 nuclear export increases fetal cardiac genes expression and plays a dominant role in the regulation of cardiac hypertrophy and heart failure." (PMID 28127553, 2017). "Several studies support a role for miR-22 in cardiac hypertrophy via targeting Pten, Sirtuin 1 (Sirt1), and histone deacetylase 4 (Hdac4) as evidenced by results from transgenic mouse models and multiple induced-hypertrophic cellular platforms." (PMID 27213331, 2016). "CaMKII exerts its effect on cardiac hypertrophy through selective phosphorylation of class II histone deacetylase 4 (HDAC4) and the subsequent activation of MEF2, which is sufficient to promote hypertrophic gene expression." (PMID 25767890, 2015). "CaMKII activates transcriptional regulators also indirectly by phosphorylating histone deacetylases, especially HDAC4, which in turn inhibits transcription factors that drive cardiac hypertrophy, fibrosis, and dysfunction." (PMID 24659967, 2014). "We previously showed that aging upregulates Nox4 and that upregulation of Nox4 in the nucleus promotes cardiac hypertrophy through oxidation and nuclear export of histone deacetylase 4 (HDAC4)." (PMID 25132912, 2014). "Consequently, targeted redox modulation of HDAC4 represents a promising independent approach for the therapeutic management of cardiac hypertrophy." (PMID 37482041, 2023). "Our previous research found that E3 ubiquitin ligase WWP1 can stabilize DVL2 by catalyzing K27-linked polyubiquitination, and DVL2 positively correlated with WWP1 hypertrophic heart and mediated the regulation of the CaMKII/HDAC4/MEF2C axis in cardiac hypertrophy by WWP1." (PMID 34733849, 2021). "Trx1 prevents cardiac hypertrophy by restoring the nuclear localization of class II HDAC4 oxidized." (PMID 31968660, 2020). "Indeed, co-culture with STVNa increased Trx1 expression and HDAC4 translocation to the cytoplasm, thereby preventing Iso-induced cardiac hypertrophy." (PMID 31968660, 2020). "Indeed, overexpression of miR-1 reduced the expression of HDAC4, and inhibition of HDAC4 gene helped attenuate TH-induced cardiac hypertrophy." (PMID 31547607, 2019). "Moreover, the endogenous cytosolic Ca2+/CN/NFAT pathway is functional in hESC-VCMs, and the overexpression of nucleus-localized CaMKIIδB led to cardiac hypertrophy through nuclear Ca2+/CaMKIIδB/HDAC4/MEF2 pathway." (PMID 31065282, 2019). "Collectively, nuclear Ca2+/CaMKIIδB/HDAC4/MEF2 pathway regulated cardiac hypertrophy in hESC-VCMs." (PMID 31065282, 2019). "Moreover, CKIP-1 can inhibit pathological cardiac hypertrophy by promoting dephosphorylation of histone deacetylase 4 (HDAC4) through recruiting serine/threonine protein phosphatase 2A (PP2A)." (PMID 28402261, 2017). "Another class II histone deacetylase involved in cardiac hypertrophy is HDAC4." (PMID 23740219, 2013).
cardiac hypertrophy (continued). "Phosphorylation of HDAC4 by CaMKII promotes nuclear export and derepression of HDAC target genes, which, in cardiomyocytes, will lead to hypertrophic growth, indicating a central role for CaMKII-HDAC4 signaling pathways in the development of cardiac hypertrophy." (PMID 24198825, 2013). "Direct oxidation of histone deacetylase 4 (HDAC4) by elevated ROS can also activate hypertrophic signaling, which is linked to the nuclear export and de-suppression of transcription factors involved in cardiac hypertrophy, such as the myocyte enhancer factor 2 (MEF2) and calcineurin-NFAT." (PMID 39594472, 2024). "In addition, HDAC4, a class II histone deacetylase, modulates cardiac hypertrophy." (PMID 31968660, 2020). "However, when we overexpressed the nucleus-targeted isoform CaMKIIδB in hESC-VCMs, we found that CaMKIIδB could indeed induce cardiac hypertrophy through nuclear Ca2+/CaMKIIδB/HDAC4/MEF2 pathway." (PMID 31065282, 2019). "Evidence supports CaMKII-dependent phosphorylation of class IIa HDACs (Ser467/Ser632 in HDAC4), linking CaMKII to MEF2 activation in cardiac hypertrophy, and interactions with NF-κB and HSF1 further expand its nuclear repertoire." (PMID 41283247, 2025). "Class II HDACs (HDAC4, 5, 7, and 9) are traditionally viewed as signal-responsive repressors of MEF2 transcription factors, thereby limiting cardiac hypertrophy under basal conditions." (PMID 41283336, 2025). "In cardiac myocytes, CaMKII phosphorylates histone deacetylase 4 (HDAC4), promoting its export from the nucleus and leading to cardiac hypertrophy." (PMID 40551210, 2025). "The nuclear accumulation of HDAC4 and HDAC5 exerts inhibitory effects on the transcriptional activity of MEF2, thereby contributing to the pathogenesis of cardiac hypertrophy." (PMID 40497340, 2025). "Numerous studies have confirmed that class II HDACs (HDAC4, 5, 7, 9, 10) inhibit the development of myocardial hypertrophy, while class I HDACs (HDAC1, 2, 3, 8) have a positive effect on myocardial hypertrophy." (PMID 38584203, 2024). "Three genes/proteins, in particular, CaMKIIδ, HDAC4, and GRK2 have been shown to act as central hubs or be directly involved in the induction of cardiac hypertrophy when misexpressed." (PMID 35890169, 2022). "CaMKIIδ, HDAC4, and GRK2 have been shown to act as central hubs or be directly involved in the induction of cardiac hypertrophy when misexpressed." (PMID 35890169, 2022). "For example, overexpression of HDAC4, HDAC5, and HDAC9 suppressed myocyte enhancer factor 2 mediated gene expression to prevent pathological stimuli-induced cardiac hypertrophy." (PMID 30721967, 2019). "In the heart, group IIa HDACs (HDAC4, HDAC5, HDAC7, and HDAC9) have been extensively studied and shown to be the endogenous inhibitors for cardiac hypertrophy." (PMID 30721967, 2019). "For instance, class IIa HDACs (HDAC4, -5, -7 and -9) can directly interact with MEF2 leading to inhibition of MEF2 activity and subsequent reduced cardiac hypertrophy." (PMID 24198825, 2013). "When exposed to OS, HDAC4 mutants rely on chromosome region maintenance protein 1 (CRM1) for their translocation into the cytoplasm, thereby abolishing the inhibitory effect of HDAC4 on cardiac hypertrophy in vivo." (PMID 37482041, 2023). "Both HDAC4 and SIRT1 have protective roles in relation to cardiac hypertrophy." (PMID 31547607, 2019). "HDAC4 and HDAC5 are signal-responsive repressors of cardiac hypertrophy." (PMID 31784580, 2019). "Among the HDACs, class IIa (HDAC4, 5, 7 and 9) are thought to be cardiac protective because overexpression of HDAC4, HDAC5, or HDAC9 in cardiac myocytes suppresses expression of a pro-hypertrophy transcription factor, Mef2 (myocyte enhancer factor-2), and reduces stress-induced cardiac hypertrophy." (PMID 36440025, 2022).
cardiac hypertrophy (continued). "However, according to other reports, chronic and high activation of NOX4 exerts negative effects following pressure overload or phenylephrine stimulation, by promoting the exclusion of histone deacetylase 4 (HDAC4) from the nucleus, thus stimulating cardiac hypertrophy." (PMID 28612009, 2017). "Studies on molecular mechanisms involved in regulating the activity of HDAC4 in cardiac hypertrophy have revealed how oxidation of conserved cysteine and the proteolysis activity of protein kinase A (PKA) are two new regulatory mechanisms of this enzyme and, thus, of cardiac hypertrophy." (PMID 23740219, 2013). "A well-known transcription factor in striated muscle biology is SRF, and Calcium/Calmodulin-dependent regulation of SRF via interaction with CaMKIV and histone deacetylase 4 (HDAC4), but not CaMKII, was demonstrated to be involved in the development of cardiac hypertrophy." (PMID 24659967, 2014).